SLC17A5 (solute carrier family 17 member 5)
Description:
Multifunctional anion transporter that operates via two distinct transport mechanisms, namely proton-coupled anion cotransport and membrane potential-dependent anion transport. Electroneutral proton-coupled acidic monosaccharide symporter, with a sugar to proton stoichiometry of 1:1. Exports glucuronic acid and free sialic acid derived from sialoglycoconjugate degradation out of lysosomes, driven by outwardly directed lysosomal pH gradient. May regulate lysosome function and metabolism of sialylated conjugates that impact oligodendrocyte lineage differentiation and myelinogenesis in the central nervous system (By similarity). Electrogenic proton-coupled nitrate symporter that transports nitrate ions across the basolateral membrane of salivary gland acinar cells, with nitrate to proton stoichiometry of 2:1. May contribute to nitrate clearance from serum by salivary glands, where it is further concentrated and secreted in the saliva. Uses membrane potential to drive the uptake of acidic amino acids and peptides into synaptic vesicles. Responsible for synaptic vesicular storage of L-aspartate and L-glutamate in pinealocytes as well as vesicular uptake of N-acetyl-L-aspartyl-L-glutamate neuropeptide, relevant to aspartegic-associated glutamatergic neurotransmission and activation of metabotropic receptors that inhibit subsequent transmitter release (By similarity). Receptor for CM101, a polysaccharide produced by group B Streptococcus with antipathoangiogenic properties.
Synonyms: AST; VEAT; SD; ISSD; NSD; SIALIN; SLD; SIASD
Tractability: Small molecule: a structure with a bound ligand is known; a high-quality ligand is known. Antibody: UniProt places it where antibodies can reach, with high confidence; its Gene Ontology location is reachable by antibodies, with high confidence; UniProt predicts a signal peptide or a membrane-spanning region; the Human Protein Atlas places it where antibodies can reach. PROTAC: ubiquitination databases record sites on it; its protein half-life has been measured; a small molecule that binds it is known.
Gene: Protein-coding gene on chromosome 6 (73,593,364 to 73,654,014, reverse strand). Ensembl gene ENSG00000119899.
Subcellular location: Basolateral cell membrane; Cytoplasmic vesicle, secretory vesicle, synaptic vesicle membrane; Lysosome membrane
Subcellular location (Human Protein Atlas): Cytosol; Plasma membrane
Pathways (Reactome):
Disease: Defective SLC17A5 causes Salla disease (SD) and ISSD
Metabolism: Hyaluronan degradation
Metabolism of proteins: Sialic acid metabolism
Transport of small molecules: Organic anion transport by SLC5/17/25 transporters
Gene Ontology:
Molecular function: D-glucuronate transmembrane transporter activity; sialic acid transmembrane transporter activity; sialic acid:proton symporter activity; carbohydrate:proton symporter activity; glucuronate transmembrane transporter activity; transmembrane transporter activity
Biological process: sialic acid transport; carbohydrate derivative transport; monoatomic anion transport; transmembrane transport; carbohydrate transmembrane transport; D-glucuronate transmembrane transport; glucuronate transmembrane transport; neurotransmitter loading into synaptic vesicle; proton transmembrane transport
Cellular component: basolateral plasma membrane; lysosomal membrane; plasma membrane; apical plasma membrane; lysosome; membrane; cytoplasmic vesicle; glutamatergic synapse; synaptic vesicle membrane
Genetic constraint (gnomAD): Loss-of-function variants: 33 observed, 41.45 expected, observed/expected ratio (o/e) 0.8, 90% interval 0.6 to 1.07. The upper end of that interval is the gene's LOEUF score, 1.07, which puts it in group 4 of 6, group 1 being the genes least tolerant of losing a copy. Missense variants: 450 observed, 524.26 expected, observed/expected ratio (o/e) 0.86, 90% interval 0.79 to 0.93. Synonymous variants: 177 observed, 193.05 expected, observed/expected ratio (o/e) 0.92, 90% interval 0.81 to 1.04.
Gene-disease validity (ClinGen):
ClinGen rates the evidence that SLC17A5 causes each of these diseases.
free sialic acid storage disease (autosomal recessive): Definitive.
Homologues: Orthologues: chimpanzee SLC17A5 (99% identical), macaque SLC17A5 (99% identical), rabbit SLC17A5 (88% identical), dog SLC17A5 (87% identical), rat Slc17a5 (86% identical), mouse Slc17a5 (86% identical), guinea pig SLC17A5 (84% identical), pig SLC17A5 (78% identical), tropical clawed frog fam200c (68% identical), zebrafish slc17a5 (64% identical), Caenorhabditis elegans slc-17.2 (39% identical), Drosophila melanogaster Picot (38% identical), and 46 more. Paralogues in human: SLC17A6 (39% identical), SLC17A8 (39% identical), SLC17A7 (38% identical), SLC17A2 (36% identical), SLC17A4 (35% identical), SLC17A1 (35% identical), SLC17A3 (33% identical), SLC17A9 (23% identical), SLC37A1 (19% identical), SLC37A2 (17% identical), SLC37A4 (17% identical), SLC37A3 (16% identical).
Diseases named in the same sentence as SLC17A5 in open-access papers:
SLC17A5 is named in the same sentence as 33 diseases in open-access papers, as found by Europe PMC text mining. Sharing a sentence is not in itself a finding about the gene and the disease. The quoted sentences say what the papers report.
Salla disease (17 papers, 2012 to 2025). Salla disease is the mildest form of the free sialic acid storage disorders, which primarily affect the nervous system. "Sialin (SLC17A5) was originally identified as the cause of sialic acid (SA) storage disease or Salla disease, and the protein has been known to mediate SA/H+ cotransport." (PMID 36838362, 2023). "Homozygous or compound heterozygous mutations in SLC17A5 cause Salla disease, first discovered in the village of Salla in Northern Finland where the founders of the Swedish family originate." (PMID 31694657, 2019). "In three patients we find a known homozygous pathogenic mutation in the Homo sapiens solute carrier family 17 member 5 (SLC17A5), causing Salla disease." (PMID 31694657, 2019). "They include ASAH1 (acid ceramidase, causing Farber disease), CLN10 (cathepsin-D, a lysosomal aspartyl proteinase causing neuronal ceroid lipofuscinosis), and SLC17A5 (sialin, causing Salla disease)." (PMID 31284408, 2019). "Salla disease is caused by mutations (including R39C and K136E) in the SLC17A5 gene encoding the transporter protein sialin of 495 amino acids." (PMID 29294191, 2018). "Mutations in the SLC17A5 gene cause also infantile sialic acid storage disease (ISSD; OMIM 269920) that represents the most severe form of lysosomal free sialic acid diseases." (PMID 26171070, 2015). "SLC17A5 was initially related to the transport of sialic acid in lysosomal membranes and associated with sialic acid storage hereditary diseases like Salla disease." (PMID 24816812, 2014). "Incorporation of forms of mouse and human SLC17A5 protein, associated with Salla disease, in proteoliposomes completely abolished the aspartate and glutamate import, whereas H+/sialic acid co-transport was significantly decreased." (PMID 24009559, 2013). "Salla disease (SD) is a disorder caused by defective storage of free sialic acid and results from mutations in the SLC17A5 gene." (PMID 23227378, 2012). "Similarly, Salla Disease is a rare autosomal recessive disorder caused by pathogenic variants in the SLC17A5 gene, which encodes sialin, a lysosomal membrane transporter of sialic acid." (PMID 41614773, 2025). "For example, the typical clinical phenotypes of Salla disease (SD; OMIM: #604369) caused by SLC17A5 mutations are hypotonia, ataxia, nystagmus, epilepsy, and findings of cerebral and cerebellar atrophy accompanied by an elevation of free urinary sialic acid." (PMID 36672937, 2023). "Salla disease and other related and often more severe sialic acid storage diseases (SASD) are caused by pathogenic variants in the SLC17A5 protein, which functions as a sialic acid transporter in lysosomes." (PMID 34831381, 2021). "Later, through WES, it was found that he was heterozygous for bi-allelic pathogenic variants in SLC17A5, consistent with Salla disease (SD), a rare lysosomal disorder with no known curative treatment." (PMID 38491427, 2024).
GM1 gangliosidosis (1 paper, 2020). A rare lysosomal storage disorder characterized biochemically by deficient beta-galactosidase activity and clinically by a wide range of variable neurovisceral, ophthalmological and dysmorphic features. "Furthermore, we detected that three other patients, an infant with GM1 gangliosidosis, an infant with MPS 3A, and an adult with type 2 elliptocytosis, were also carriers of confirmed pathogenic mutations in the SMPD1, SLC17A5, and HEXB genes, respectively." (PMID 32071839, 2020).
lysosomal storage disorders (1 paper, 2013). "Mutations in the SLC17A5 gene, encoding sialin, can elicit two autosomal recessive lysosomal storage disorders: Salla disease and infantile sialic acid storage disease (ISSD)." (PMID 24009559, 2013).
sialuria (1 paper, 2017). "It should also be mentioned that SASD has been reported in two siblings without sialuria, both homozygous for the Lys136Glu mutation in SLC17A5." (PMID 28187749, 2017).
neurodegenerative disease (2 papers, 2025). A disorder of the central nervous system characterized by gradual and progressive loss of neural tissue and neurologic function. "Lysosomal free sialic acid storage disorder (FSASD) is a rare neurodegenerative disease caused by biallelic mutations in SLC17A5, encoding the lysosomal sialic acid exporter, SLC17A5 (sialin)." (PMID 40804080, 2025). "Lysosomal free sialic acid storage disorder (FSASD) is a rare, multisystem neurodegenerative disease caused by biallelic pathogenic variants in SLC17A5, encoding sialin." (PMID 40529477, 2025).
autosomal recessive disease (1 paper, 2022). Autosomal recessive form of disease. "Our data suggests a higher risk for some autosomal recessive diseases in Acadians, notably those associated with AIRE, BCHE, ETFDH, RAPSN and SLC17A5 (2 variants)." (PMID 35488281, 2022).
cancer (1 paper, 2025). A tumor composed of atypical neoplastic, often pleomorphic cells that invade other tissues. "Our findings reveal that miR-142-3p overexpression not only reduces ULK1 protein levels but downregulates lysosomal function-associated gene SLC17A5, and the autophagosome–lysosome attachment gene STX12, highlighting its potential to disrupt autophagy and lysosomal processes in cancer cells." (PMID 40362400, 2025).
SLC17A5 also shares sentences with these, for which no sentence is quoted: Ataxia (2 papers); epilepsy (2); Infantile Sialic Acid Storage disease (2); Alexander disease (1); Cerebellar atrophy (1); developmental delay (1); Dystonia (1); erythropoietic porphyria (1); Farber disease (1); fetal hydrops (1); Gaucher disease (1); glycogen storage disease IV (1); hereditary cancer (1); hydrops (1); Intellectual disability (1); leukoencephalopathies (1); Lipid storage disease (1); microcephaly (1); mucopolysaccharidosis type 7 (1); Nystagmus (1); Pelizaeus-Merzbacher Disease (1); Pelizaeus-Merzbacher-like disease (1); progressive ataxia (1); Tremor (1); tumor (1); type 2 elliptocytosis (1).